IDH1 (isocitrate dehydrogenase (NADP(+)) 1)
Diseases named in the same sentence as IDH1 in open-access papers (continued):
Sharing a sentence is not in itself a finding about the gene and the disease.
tumor (continued). "Thus, understanding how IDH1 mutation affects checkpoint signaling may reveal ways to further sensitize IDH1 mutant tumor cells to TMZ." (PMID 28178660, 2017). "IDH1 status can also distinguish different glycolytic phenotypes of GBM, which may contribute to the different clinical behaviour of tumours with and without the IDH1 mutations." (PMID 28804724, 2017). "Interestingly, IDH1 mRNA levels were found to be lower in the GB10 model which also may explain the lower levels of tumor 2-HG in vivo." (PMID 29062039, 2017). "Indeed, the observed low expression of a large constituent of the proneural gene set in GB10 suggests that this tumor type may be quite different than most IDH1 mutant patient tumors." (PMID 29062039, 2017). "From what has been mentioned so far, it is clear that IDH1 R132 and IDH2 R172 mutations in these types of tumor, whether they occur as early or late ones, are driver mutations and that stresses on the importance of targeting them as a candidate anticancer therapy." (PMID 28785398, 2017). "The roles of reactive astrocytes, tumor associated microglia and macrophages, metabolic alterations, microsatellite instability, O6-methylguanine DNA methyltransferase (MGMT) DNA repair and epigenetic alterations mediated by the isocitrate dehydrogenase 1 (IDH1) mutations have been discussed." (PMID 28346397, 2017). "Followed by further examination and verification, we confirmed clomifene, an effective and low-cost medication for ovulation induction, as a novel inhibitor of mutant IDH1, which could reduce the cellular and tumor levels of D-2HG, showing dramatically on-target activity both in vitro and in vivo." (PMID 28498812, 2017). "The factors correlated with longer OS included age ≤40 (P<0.001), KPS ≥70 (P=0.006), total resection of tumor (P=0.001), tumor size <6 cm (P=0.034), Ki-67 <20% (P<0.001), lower tumor grade (P<0.001), 1q/19p co-polysomy (P<0.001), no single polysomy (P<0.001), and IDH1/2 mutation (P=0.001)." (PMID 28978019, 2017). "IDH1 could also influence tumour phenotype by regulating HIF1α (refs 6,7,23,24)." (PMID 27820599, 2016). "We performed xenograft injections of R132H IDH1 cells expressing either WT or V737N β1 integrin to test whether enhancing cellular mechanosignalling in mutant GBMs would increase tumour aggression and, if so, whether this increase would be associated with elevated HIF1α and TNC expression." (PMID 27820599, 2016). "Lesion border sharpness, on the other hand, as evaluated by Prewitt filtering of the image, could not predict IDH1 mutation status of the tumor." (PMID 27716832, 2016). "Together, our findings show that expression of mutant Idh1 recapitulates cellular and molecular features of gliomagenesis, including stem cell features, increased proliferation, infiltration into adjacent structures, and tumor-like nodules originating from nestin-expressing cells." (PMID 27693047, 2016). "As a further line of interest, the detection of elevated D2HG concentrations in different tumor entities may identify elevated D2HG levels as a surrogate marker, eventually in combination with the distribution of lactate, for tumor-relevant IDH1 and IDH2 mutations." (PMID 27014623, 2016). "However, a few tumor cells existed outside of the margin of the foci-tumor region, and the diffused tumor cells were confirmed in an immunochemistry stained image (isocitrate dehydrogenase 1 [IDH1, 1/80, clone H09, Dianova, Germany] stain, Materials and Methods) and not in a H&E stained image." (PMID 27782153, 2016). "The mutual exclusivity between IDH1/2 and PTEN mutations suggests that abrogation of PTEN function might not confer a growth advantage to tumours carrying IDH1/2 mutations, allowing speculation that IDH1/2 mutations mimic PTEN loss or inactivation." (PMID 27624942, 2016).
tumor (continued). "Independent of the tumor grade, we also found a dramatic increase in survival in patients presenting IDH1 mutation (29.2 months), suggesting that this gene is an important biomarker, as the authors have previously found that IDH mutation was the main driver of the clusters." (PMID 27172220, 2016). "Of note, this tumour was not harbouring any IDH1/2 mutation or MYCN amplification." (PMID 26399631, 2015). "Although IDH1/2 mutations might not directly trigger tumorigenesis, they increase the risk of other tumor-promoting mutations that cooperate with IDH mutations to induce gliomagenesis." (PMID 26338964, 2015). "Robbins also demonstrated that decreased IDH1 expression might be correlated with tumor promotion." (PMID 26376762, 2015). "The 2-HG levels, measured using MRI, correlate 100% with whether the tumor has a mutation in IDH1 or IDH2, again without the need to get any tissue." (PMID 24581008, 2014). "That’s important for two reasons: first – because the tumor is more likely to be lower grade, that is, less aggressive, if there is a mutation in IDH1 or IDH2; and second – drugs have now been developed specifically to inhibit the mutant isoforms of IDH1 and IDH2 that occur in these tumours." (PMID 24581008, 2014). "So it becomes possible to tell the patient on the day of the MRI scan whether or not there is an IDH1 or IDH2 mutation in the tumour." (PMID 24581008, 2014). "Overall, it is tempting to speculate that, like in the haematopoietic system, absence of TET2 activity, either by IDH1/2 mutations or by promoter methylation, promotes self-renewal of tumour-initiating cells for low-grade diffuse gliomas." (PMID 23998913, 2013). "IDH1, encoding two TCA enzymes, fumarate hydratase (FH) and succinate dehydrogenase (SDH), has been found to sustain loss-of-function mutations in certain human tumors, which likewise contribute to tumor growth via stimulating the HIF-1a pathway and mutationally altering metabolic enzymes." (PMID 20459648, 2010). "Established biomarkers, including IDH1, MGMT, and EGFR, provide crucial insights into the tumor's biology and are essential for guiding therapy decisions." (PMID 40223032, 2025). "Ultrasound findings exhibited statistically significant differences between IDH1 mutant and wild type for peritumoral edema, blood flow architecture of SMI peritumoral tissue, and blood flow architecture of SMI tumor tissue." (PMID 40944023, 2025). "Immunohistochemistry demonstrated positivity for IDH1 R132H mutant protein and ATRX expression was retained in tumor nuclei." (PMID 39857783, 2025). "FGFR2+ tumors also demonstrated separation between both CD4+ T cells and CD8+ T cells and tumor cells as compared to both IDH1+ iCCA and FGFR2 WT/IDH1 WT (p<0.001)." (PMID 39969434, 2025). "For our assays, we collected 10 tumors (3 LGG IDH1/2mut, 5 HGG tumors, and 2 HGG IDH1/2 mut) and performed KAT5 activity and protein synthesis assays (30 min treatment with O-propargyl-puromycin (OPP)) in match cohorts of tumor cells." (PMID 40346033, 2025). "Targeting tumor drivers such as FGFR, IDH1/2, PI3K-AKT-mTOR, MEK/ERK, and YAP/TAZ in combination with metabolic inhibitors offers a promising strategy to overcome resistance to ICIs." (PMID 41394868, 2025). "αSMA+ fibroblasts were close to tumor cells in both FGFR2+ and IDH1+ tumors, compared to other subtypes, highlighting their potential roles in mediating interactions among the included cell types." (PMID 39969434, 2025). "In order to identify common changes across all patients, multilevel modelling was performed on patients 6, 8, 9, 14, and 15, covering IDH1 wildtype GBM, IDH1 mutant GBM, and MGNT tumour types." (PMID 39816516, 2025).
tumor (continued). "Then, we conducted in vivo experiment where ivosidenib (50 mg kg−1), an IDH1 mutant enzyme inhibitor, was orally administered to TS603 (IDH1‐MUT) and U251 (IDH1‐WT) tumor‐bearing nude mice." (PMID 40171868, 2025). "Our findings showed that higher catalytic activity afforded by IDH1 R132Q versus R132H led to increased D2HG levels in cells, tumor tissue, and sera, and larger tumors upon expression of this highly kinetically active mutant, despite its lower expression." (PMID 40188944, 2025). "Notably, increased expression of several ROS hallmark genes involved in antioxidant response—Idh1, Nfe2l2 (NRF2), and Glrx—were validated by reverse transcription quantitative polymerase chain reaction (RT-qPCR) in both tumor-derived cell lines and whole tumor lysates." (PMID 40802750, 2025). "Therapeutically, FDA-approved inhibitors ivosidenib (IDH1) and enasidenib (IDH2) reduce D-2HG levels, restore differentiation, and enhance anti-tumor immunity in AML, demonstrating clinical efficacy." (PMID 40734168, 2025). "Mutant IDH1 (mIDH1) drives immune exclusion via metabolic reprogramming of the TME, and preclinical models show that IDH inhibition can restore anti-tumor immunity." (PMID 41138165, 2025). "Conversely, IDH1+ iCCA had closer spatial interactions between CD4+ T cells and tumor cells as compared to the other molecularly defined groups (p<0.001)." (PMID 39969434, 2025). "Multivariate Cox regression analysis identified age, Karnofsky Performance Status (KPS) score, tumor diameter, WHO grade, and postoperative radiotherapy and chemotherapy, as well as the expression of ATRX, IDH1, and Ki-67, as independent prognostic factors." (PMID 41008886, 2025). "The distance between CD11b+/CD15+ granulocytes and tumor cells, as well as both CD8+ and CD4+ T-cell subsets, was reduced as compared to IDH1+ iCCA and FGFR2 WT/IDH1 WT iCCA (p<0.001 for all comparisons)." (PMID 39969434, 2025). "In this study, a nomogram model was developed by integrating tumor immune markers (ATRX, IDH1, Ki-67) and clinical characteristics (age, WHO grade, postoperative radiotherapy and chemotherapy)." (PMID 41008886, 2025). "Metabolic inhibitors (IDH1/2, LDH inhibitors) reprogram tumor metabolism to reduce immune suppression." (PMID 40223940, 2025). "The landmark INDIGO trial led to the first FDA approval of the IDH1/2-mutant inhibitor, vorasidenib, for IDH-mutant glioma, representing the first approval of a systemic targeted therapy for this tumor type." (PMID 40867259, 2025). "This aligns with recent studies showing that nuclear FABP7 levels are higher in wild-type IDH1 malignant GBM tumors compared to IDH1-mutant LGG tumors, differentially regulating cell proliferation and migration in these distinct tumor types." (PMID 39596296, 2024). "In IDH-1 group, ADC images showed 367 tumor features, APTW images showed 323 tumor features, Ktrans images showed 478 tumor features, and Ve images showed 321 tumor features (all P < 0.05)." (PMID 39285364, 2024). "Several promising molecular markers with prognostic significance were also identified, including tumour HMGA2, MUC5AC/6, IDH1, PIWIL2, and DNA index." (PMID 38398089, 2024). "Moreover, IDH1 mutation-driven mouse models of similar solid tumors do not exhibit tumor regression upon removal of the IDH1 mutation, implying a limited efficacy of IDH1 mutation inhibitors when used as monotherapy in tumors with comparable pathological conditions." (PMID 39156971, 2024).
tumor (continued). "Specifically, IDH1 established the CpG island methylator phenotype (CIMP), characterized by extensive epigenetic aberrations and a powerful determinant of tumor pathogenicity." (PMID 39123479, 2024). "We intend to investigate the IDH1 and IDH1R132H tumor-bearing animals with comparable tumor size, homogeneous T2-weighted signal and positive contrast-enhanced T1-weighted MR images." (PMID 37982850, 2024). "Further investigations have revealed that IDH1 can selectively bind CD8 dimers and enhance immunotherapy effects by augmenting T-cell responsiveness to multiple tumour antigens." (PMID 38660136, 2024). "Accordingly, IDH1 status, a defining feature of different tumours, has been included in the WHO Central Nervous System Tumour Classification in 2016." (PMID 37273917, 2023). "As neurocognitive impairment consists of a core domain of the clinical symptoms that tumor patients show, one would assume that IDH1 wild-type HGG would induce more severe neurocognitive deficits compared to their IDH1 mutant-type counterparts." (PMID 36970174, 2023). "However, Idh1 mutation alone was not sufficient to drive tumor development." (PMID 36765553, 2023). "We treated PDXs with selective pharmacologic inhibitors of IDH1 and FGFR alterations and confirmed tumor growth depended on these alterations." (PMID 36611031, 2023). "To initially compare IDH1-mutant and IDH-wt tumors, we investigated the tumor cell compartment (T and K samples)." (PMID 38077210, 2023). "Ivosidenib, a mutant IDH1 inhibitor, completed its phase III trials, demonstrating a positive impact on PFS and OS in patients with IDH1 mutant ICC tumor progression despite adequate chemotherapy." (PMID 37174089, 2023). "Since we demonstrated that PNA was able to suppress amplification of WT IDH1, and LAMP amplified IDH1 in tumor lysates, we next sought to evaluate if CPNA-LAMP can specifically detect IDH1-R132H using tumor lysates." (PMID 37733671, 2023). "This reveals large differences between IDH1-mutant and IDH-wt tumors; most notably the increase of mesenchymal (P < .001) and progenitor (P < .001) tumor cells in IDH-wt compared to IDH1-mutant." (PMID 38077210, 2023). "These neoplasms are frequently categorized based on specific genetic changes such as FGFR1, MYB/MYBL1, BRAF, or IDH1/2, identified through DNA methylation profiles." (PMID 38137148, 2023). "It has also been found that tumor driver genes IDH1/2, JARID1C/KDM5C and UTX/KDM6A can regulate histone demethylation and thus affect cancer metabolism and tumor progression." (PMID 36941564, 2023). "This assay was evaluated using IDH1-WT or IDH1-R132H mutant synthetic DNA, wild-type or IDH1-R132H mutant U87MG cell lysates, and tumor lysates from archived patient samples in which the IDH1 status was previously determined using immunohistochemistry (IHC)." (PMID 37733671, 2023). "Unfortunately, most GBM are IDH-1 wild type and unmethylated MGMT becomig aggressive and resistant to therapies included the new immune checkpoint inhibitors due to the “cold tumor” phenotype." (PMID 37584750, 2023). "Here, we provide a spatial characterization of the tumor microenvironment in IDH wild-type and IDH1-mutant HGG, revealing vast heterogeneity and discrete interactions between tumor cell states and immune cells within a highly organized tumor architecture." (PMID 38077210, 2023).
tumor (continued). "In comparison with IDH1-wt patients, patients with IDH1-mut (17%), were significantly younger, had better performance status and more often they had Grade III tumour." (PMID 37341199, 2023). "Histopathological and molecular characterization of tumors was achieved considering tumor grade according to 2016 WHO and several biomarkers (i.e., IDH-1, TERT, MGMT, DEL1p/19q, Ki-67)." (PMID 35720068, 2022). "Distributions of tumor MGMT status and EGFR, TERT, and IDH1 genomic alterations observed in the current study are consistent with those reported in the current literature." (PMID 34510238, 2022). "Patient-derived surgical specimens were subjected to molecular analysis, which revealed the tissue to be GBM with the tumor cells highly expressing GFAP, Ki67, and IDH1 R132H." (PMID 35646111, 2022). "As a tumor suppressor, the global autophagy regulator TFEB is required to regulate IDH1/2 expression and induces myeloid differentiation by controlling IDH1/2-TET axis." (PMID 35526025, 2022). "Tumor cells were positive for O-6-methylguanine-DNA methyltransferase (MGMT) and IDH1, with a proliferation activity of 2% for Ki-67." (PMID 35991838, 2022). "Several genes were found at lower expression levels in tumor cases, such as AXL, BAHC2, CFLAR, and DNMT1 while others were overexpressed such as BNIP3, DIABLO, FADD, and IDH1." (PMID 35911707, 2022). "Sex, age, tumor size (≥3.0 cm), extent of resection, WHO classification (High grade), IDH1 status (Mutant), Ki-67 expression (≥10%), and MAGED2 protein expression were used to categorize patients." (PMID 35892426, 2022). "We showed that patient age at diagnosis increased across grades in these groups and that the median age was highest in those with IDH2 tumours (IDH1: 55 year, IDH2: 67 year, IDHwt: 47 year, IDH1 vs IDH2: p = 0.003, IDH1 vs IDHwt: p = 0.0006)." (PMID 36042521, 2022). "Immunohistochemical testing to assess the distribution of the mutant IDH1 and IDH2 proteins within the tumour was unfortunately unable to be performed, and is a limitation of our study of this case." (PMID 36286062, 2022). "In G2/3 tumours, the activity of SBS5 was similar in IDH1 and IDH2, but lower in IDHwt (IDH1 vs IDH2 p = 0.4, IDH1 vs IDHwt: p = 0.03)." (PMID 36042521, 2022). "Silencing of IDH1 slows GBM growth, prolongs the survival of mice carrying patient-derived xenografts, and promotes tumor cell differentiation and tumor cell apoptosis." (PMID 36497259, 2022). "Here, a comparison of gene expression between PLEKHM3 and IDH1 across the GBM tumor revealed the opposite trends, whereby PLEKHM3 was upregulated in the leading edge and downregulated in the cellular tumor." (PMID 35877430, 2022). "The overall methylation level across all probes also revealed significant differences between IDH1 and IDH2 tumours (p = 0.002) indicating that the former are globally hypermethylated compared to IDH2 and IDHwt tumours." (PMID 36042521, 2022). "Specifically, D-2- hydroxyglutaric acid, a metabolite produced by mutant IDH1 in tumor cells, reduces the expression of antioxidant GPX4 in tumor cells, thus enhancing the ferroptosis sensitivity induced by Erastin." (PMID 36237575, 2022). "In line with its neomorphic activity, mutant IDH1 GBM engrafted in mouse brain display high levels of D2HG and exhibit very slow tumor growth." (PMID 34764443, 2022). "Each of these potential prognostic biomarkers was negatively correlated with IDH1 and significantly downregulated in GBM compared to non-tumor." (PMID 35877430, 2022).